ARG1 (arginase 1)
Diseases named in the same sentence as ARG1 in open-access papers (continued):
Sharing a sentence is not in itself a finding about the gene and the disease.
amyloid (continued). "Collectively, this argues that amyloidosis triggers expression in key Ragulator–Rag complex components critical for lysosomal digestion and that proper Arg1 function may be required for this response." (PMID 33519806, 2020). "In our study, APP/Arg1 insufficient mice showed increased CD68 expression in HPC and ECX compared to APP/Arg1 sufficient mice and nTg/Arg1 insufficient mice, suggesting that amyloidosis and Arg1 deficiency promoted CD68 expression." (PMID 33519806, 2020). "Therefore, proper Arg1 levels in microglia/myeloid cells become critical for activating phagocytic responses during challenges such as amyloidosis." (PMID 33519806, 2020). "Therefore, we argued that the Arg1 expression in myeloid cells was predicted to be a compensatory response to restrict amyloidosis in AD." (PMID 33519806, 2020). "However, reduced Ragulator-Rag complex in APP mice with Arg1 insufficiency during amyloidosis indicated that arginine metabolism has an unappreciated role in executing this function at the level of the lysosome." (PMID 33519806, 2020). "Our results showed that reduced Arg1 levels in LysM positive cells promoted amyloidosis in CNS." (PMID 33519806, 2020). "This is consistent with in vitro findings that IL-4-treated microglia are potentially more efficient phagocytes, as well as an in vivo finding in which elevated Arg1 and reduced iNOS mRNA correlated with greater Aβ microglial phagocytosis and reduced amyloid plaque load." (PMID 26538310, 2015). "However, given the relationship between ARG1-arginine and arginine-Ragulator-Rag-mTORC1-axis, it is possible that myeloid-specific demands for Arg1 are required in response to amyloidosis and that uncoupling of phagocytosis/digestion initiates increased Aβ deposition." (PMID 33519806, 2020). "However, currently, it remains unknown if the reduction of arginase 1 (Arg1) in myeloid cell impacts amyloidosis." (PMID 33519806, 2020). "To determine the impact of reducing Arg1 in a mouse model of amyloidosis, we obtained 33 DEGs (p < 0.05) in comparison of APP/Arg1 insufficient mice to APP/Arg1 sufficient mice." (PMID 34046031, 2021). "Probably, Arg1 and NOS2 activities, their respective byproducts, and arginine depletion/repletion are temporally critical regarding microglial response to amyloidosis." (PMID 33519806, 2020).
B-cell lymphoma (6 papers, 2017 to 2023). "Interestingly, in a pre-clinical mouse model of B cell lymphomas, Ly6Clow monocytes (corresponding to the ncMO) accumulated and showed high levels of immunosuppressive genes (PD-L1, PD-L2, Arg1, IDO1, and CD163) associated with suppression of T cell proliferation." (PMID 34975843, 2021). "used a B-cell lymphoma model to link the expression of ARG1 to MDSCs proliferation and expansion." (PMID 33679700, 2020). "Treg generation may be influenced by MDSCs as has been suggested by several studies, and Arg1 has been directly pointed out to be responsible for Treg development in a preclinical B cell lymphoma model." (PMID 28423487, 2017). "MDSCs promote the formation of T regulatory cells (Tregs), the secretion of immunosuppressive IL-10 and TGF-β, and inhibit the activity of cytotoxic CD8 T cells via expression of arginase-1 (Arg1) and inducible nitric oxidase (iNOS) within the TME of several tumor entities including B cell lymphoma." (PMID 33343570, 2020).
cystic fibrosis (6 papers, 2012 to 2023). Autosomal recessive disorder caused by pathogenic variants in the CFTR gene (cystic fibrosis transmembrane conductance regulator), which encodes a chloride and bicarbonate channel expressed in epithelial cells, and follow the diagnosis criteria. "We showed here that instillation of “sterile” agarose beads in a rat biofilm model, extensively used in the field of cystic fibrosis research, activates the same Th2 cytokines (IL-5 and IL-13) and Th2 innate cells (eosinophils and Arg1+ M2 macrophages) as observed in human CF patients." (PMID 28680858, 2017). "For example, through secretion of arginase-1 (Arg1) they suppress T-cell proliferation in the airways of cystic fibrosis patients and limit T-cell function in the tumor microenvironment." (PMID 32013006, 2020). "PMNs, which is recruited massively into the cystic fibrosis lumen, could modulate arginase 1 and suppress the early PMN-driven T cell in CF." (PMID 28589151, 2017).
diabetic retinopathy (6 papers, 2013 to 2025). "In the current study, we explored the possible association of the rs2781666 single nucleotide polymorphism in the ARG1 gene with susceptibility to diabetic retinopathy in T2DM patients." (PMID 34830689, 2021). "In this analysis, only ARG1 rs2781666 SNP was found to be a significant risk predictor of diabetic retinopathy (p = 0.003)." (PMID 34830689, 2021). "The objective of our preliminary case–control study was to analyze the potential association between the ARG1 rs2781666 SNP (selected on the basis of its position and/or putative functionality) and diabetic retinopathy in T2DM patients." (PMID 34830689, 2021). "Our findings show that the rs2781666 SNP in the ARG1 gene is significantly associated with increased susceptibility to diabetic retinopathy in T2DM patients." (PMID 34830689, 2021). "Notably, in mouse models of endotoxin induced uveitis and diabetic retinopathy, an elevated expression of ARG1 in RMG has been associated with immune regulated pro-inflammatory responses such as the uncoupling of enzymes of the nitric oxide synthase (NOS)-family." (PMID 40001591, 2025). "The mechanism by which the rs2781666 SNP in ARG1 gene confers susceptibility to diabetic retinopathy is not clear and needs to be explored." (PMID 34830689, 2021). "This study highlights the role of arginase 1 in inducing EC senescence during diabetic retinopathy." (PMID 29673160, 2018). "However, since arginase 1 has complex functions that depend on the vascular cell type, whether this hypothesis applies to diabetic retinopathy requires more extensive study in the future." (PMID 34830689, 2021).
fungal infection (6 papers, 2011 to 2024). "Both ARG1 and CARG were induced by fungal infection, with only ARG1 showing a significantly larger induction in both genotypes." (PMID 35018449, 2022). "The data suggested that alveolar macrophages, a large fraction of which expresses Arg1 after fungal infection, can efficiently phagocytose conidia." (PMID 21246055, 2011). "We show that after fungal infection, AAMs expressing Arg1, Ym1 and CD206 develop in the lung as early as 6 hours after infection." (PMID 21246055, 2011). "Fungal infection rapidly induced Arg1 expression in alveolar macrophages, which was also true for tissue macrophages (not shown)." (PMID 21246055, 2011). "Since the majority of the alveolar macrophages expressed Arg1 after fungal infection, we were curious whether the CD11c+ cells isolated and purified from BAL fluid had the ability to phagocytose fungal conidia." (PMID 21246055, 2011). "Arg1 induction upon fungal infection was partially dependent on the IL-4Rα/STAT6 signaling axis." (PMID 21246055, 2011). "Our study also found that after fungal infection, Dectin-1 affected the expression levels of phenotype-related factors (TNF-α, INOS, IL-6, IL-12, Arg-1, or IL-10) in M1 and M2-type macrophages through the regulation of MAPK signaling pathways, such as p38, JNK, and ERK." (PMID 39478855, 2024). "The analysis of the M1/M2 (NOS2/ARG1 and SOCS3/SOCS1) ratios expressed by A/J and B10.A cells demonstrates that curdlan increases but laminarin decreases the M1/M2 ratios of A/J macrophages induced by fungal infection." (PMID 26388856, 2015).
head and neck cancer (6 papers, 2020 to 2023). A primary or metastatic malignant neoplasm affecting the head and neck. "Using multiplex staining, ARG1 expression has been associated with tumor-associated macrophages in HPV- head and neck cancers and poor prognosis." (PMID 37046826, 2023). "Head and neck cancer creates a highly immunosuppressive microenvironment, to which the enzyme Arginase-1 contributes." (PMID 38001706, 2023). "The impact of Arginase-1 on the clinicopathology and prognosis of head and neck cancer, however, is not fully understood." (PMID 38001706, 2023). "Ongoing clinical trials testing the efficacy of ARG1 mimics are underway and include recruitment of various cancer types such as liver, blood, head and neck cancers." (PMID 34885177, 2021). "ARG1 levels in MDSCs from patients with head and neck cancer were regulated by STAT3 signaling." (PMID 32499785, 2020). "For example, genes that play a role in the inflammatory response such as ARG1, BCL2L1 (upregulated) and MYC (downregulated) were found in blood of patients undergoing radiotherapy treatment for endometrial or head and neck cancers." (PMID 34638945, 2021). "A more recent study showed that a purified ARG1 mimic (arginine deaminase conjugated with polyethylene glycol) inhibited some but not all head and neck cancer cell growth in vitro." (PMID 34885177, 2021). "Considering the nonauxotrophic nature of head and neck cancer together with its heightened ability to synthesize arginine, high doses of ARG1 mimics would theoretically be required to ‘starve’ this cancer type." (PMID 34885177, 2021).
influenza (6 papers, 2018 to 2025). An acute viral infection of the respiratory tract, occurring in isolated cases, in epidemics, or in pandemics; it is caused by serologically different strains of viruses (influenzaviruses) designated A, B, and C, has a 3-day incubation period, and usually lasts for 3 to 10 days. "Likely, PPAR-γ deficiency increased Arg1 expression in lung macrophages at 30 days post influenza infection." (PMID 31584978, 2019). "During influenza infection in mice, induction of Arg1 expression is a key feature of lung CD4+ T cells." (PMID 39858200, 2025). "We found increased numbers of iNOS+F4/80+ and Arg1+F4/80+ cells during influenza infection and super-infection in Stat2−/− mice compared to WT mice." (PMID 30337919, 2018). "Further, these M1/M2 cells had increased expression levels of both Arg1 and Nos2 in Stat2−/− mice during influenza-bacterial super-infection." (PMID 30337919, 2018). "The exosomes of the infected A549 cells were found to enhance M1 polarization (iNOS/Arg-1, Tnfα/Arg-1, and IL-1β/Arg-1) in a better way, thereby indicating that exosomes might play an essential role in influenza-mediated macrophage polarization." (PMID 35371077, 2022). "Interestingly, ARG1 (arginase 1) was one of the most abundant transcripts found in severe influenza patients." (PMID 32066441, 2020). "However, PPAR-γ deficiency did not alter the expression of M2 genes, Arg1 and Retnla (encodes Relmα) expression following influenza exposure." (PMID 31584978, 2019). "Neutralization of IFNγ (M1) and/or Arginase 1 (M2) impaired bacterial clearance in Stat2−/− mice during super-infection, demonstrating that pulmonary macrophages expressing a mixed M1/M2 phenotype promote bacterial control during influenza-bacterial super-infection." (PMID 30337919, 2018). "In contrast, we observed a decrease in the number of Arg1+F4/80+ cells in MRSA and super-infection compared to WT mice infected with influenza alone." (PMID 30337919, 2018). "Next, we found increased gene expression of Nos2 and Arg1 in Stat2−/− mice when compared to WT mice during influenza, but not MRSA infection." (PMID 30337919, 2018). "To determine whether the increase in M1 and M2 macrophages is influenza or MRSA dependent, we infected WT or Stat2−/− mice with influenza or MRSA or super-infection, and determined the number of iNOS+F4/80+ and Arg1+F4/80+ macrophages in the lung by IHC." (PMID 30337919, 2018). "However, in Stat2−/− mice the Arg1+ cells were increased in influenza-bacterial super-infection, but not MRSA infection, suggesting that the M2 induction during super-infection is driven by influenza infection." (PMID 30337919, 2018). "Arg1 was neutralized using nor-NOHA in both WT and Stat2−/− mice subjected to influenza/MRSA super-infection." (PMID 30337919, 2018).
leukemia (6 papers, 2021 to 2024). A malignant (clonal) hematologic disorder, involving hematopoietic stem cells and characterized by the presence of primitive or atypical myeloid or lymphoid cells in the bone marrow and the blood. "Interestingly, flow cytometry revealed that the percentage of TCL1 leukemia-associated neutrophils expressing PD-L1 and ARG-1 was increased at the late stage of disease, whereas the percentage of IDO- and IL4R-expressing cells was higher at the early stage." (PMID 37817276, 2023). "We found that inhibition of MerTK decreased leukemia-associated macrophage expression of M2 markers PD-L1, PD-L2, Tim-3, CD163 and Arginase-1 compared to vehicle-treated controls." (PMID 36960055, 2023). "Additionally, the late stage of disease was associated with a higher percentage of neutrophils expressing ARG-1 than the early stage of leukemia." (PMID 37817276, 2023). "Furthermore, the expression of most M2-associated genes, such as Arg1, CCL3, CCL17, CD206, IL-10, and TGF-β decreases with the infiltration of leukemia cells, whereas the expression of MMP9 and VEGFα increases in the advanced stages of leukemia." (PMID 38779660, 2024). "In vitro co-culture experiments showed that MSCs could significantly up-regulate the expression of Arg1, a marker of tissue repair, in L-Macs, and the expression of Arg1 in macrophages isolated from the bone marrow of MSC-treated leukemia mice was also significantly increased." (PMID 38779660, 2024). "Another study showed that healthy MSCs implantation could induce the activation of Arg-1+ macrophages in the bone marrow of ALL mice, repair damaged BMME, and delay the progression of leukemia." (PMID 38779660, 2024). "Targeting efferocytic macrophages within the spleen and marrow leukemia microenvironments, we demonstrated that MRX2843 decreased macrophage immunosuppressive features including a reduction in M2-like markers PD-L1, PD-L2, Tim-3, CD163, and Arginase-1." (PMID 36960055, 2023).
malaria (6 papers, 2016 to 2021). Malaria is a serious and sometimes fatal disease caused by a parasite that commonly infects a certain type of mosquito which feeds on humans. "Plasma arginase is associated with arginine depletion in malaria, which is consistent with our hypothesis that hepatic Arg1 depletes arginine." (PMID 34607466, 2021). "In support of our bioinformatic data, we found that plasma arginase activity in malaria was reduced only in liver-specific Arg1 knockout mice." (PMID 34607466, 2021). "Plasma arginase activity is increased in malaria patients, but it has been attributed to other sources of Arg1 such as red blood cells or monocytes." (PMID 34607466, 2021). "Investigations in children infected with malaria showed increased levels of arginase 1 and IL-10, reduced amounts of NO, and increased expression of M2 markers (CD163, CD206)." (PMID 33330947, 2021). "We confirmed that hepatic Arg1 was the primary source of increased plasma arginase activity in our model, which motivates further investigation of liver damage in human malaria patients." (PMID 34607466, 2021). "We showed that P. chabaudi-induced liver damage releases arginine-consuming hepatic arginase-1 (Arg1) into circulation, which explains increased plasma arginase activity in our model and may explain elevated plasma arginase in human malaria." (PMID 34607466, 2021). "Likewise, PBMC arginase 1 protein was higher in children with malaria than in HC children." (PMID 27385484, 2016). "Among these genes, some were previously shown to play a role in severe malaria, specially CXCL10, ARG1, ATP2B4, and MMP9." (PMID 32801995, 2020). "One of the proposed causes, although controversial, of l-Arg depletion is the increase of arginase activity generated by parasites or host cells, but no report in the literature seems to link malaria haemozoin and arginase-1 activation, so far." (PMID 30522493, 2018). "PBMC arginase 1 mRNA was markedly elevated and NOS2 lower in children with malaria." (PMID 27385484, 2016).
metastatic carcinoma (6 papers, 2012 to 2023). A carcinoma which has spread from the original site of growth to another anatomic site. "They all recommend to use of Arg-1 with HepPar-1 and glypican-3 as a panel in distinguishing HCC from metastatic carcinoma." (PMID 37874737, 2023).
sickle cell disease (6 papers, 2021 to 2025). Sickle cell anemias are chronic hemolytic diseases that may induce three types of acute accidents: severe anemia, severe bacterial infections, and ischemic vasoocclusive accidents (VOA) caused by sickle-shaped red blood cells obstructing small blood vessels and capillaries. "In several hemolytic disorders like sickle cell disease, thalassemia, and paroxysmal hemolytic ureamia, arginase-1 is released from erythrocytes into the plasma causing NO depletion and secondary pulmonary hypertension." (PMID 34599427, 2022). "Arginase 1 is released during hemolysis and elevated levels have been described in hemolytic diseases, such as sickle cell disease and thalassemia." (PMID 38178089, 2024). "Arginase 1 is released from lysed RBCs in other hemolytic conditions such as sickle cell disease, beta-thalassemia, and paroxysmal nocturnal hemoglobinuria." (PMID 38178089, 2024). "As has been shown for other hemolytic disorders such as paroxysmal nocturnal hemoglobinuria or sickle cell disease, arginase-1 is released from lysed erythrocytes and leads to vasoconstriction by L-arginine consumption." (PMID 37122295, 2023). "In humans and other primates, red blood cells (RBCs) constitutively express high levels of liver-type arginase 1 (Arg1), which regulates systemic l-arginine and nitric oxide (NO) bioavailability, particularly under pathological conditions such as sickle cell disease." (PMID 40729962, 2025). "Arg1 inhibitors are currently in early phase clinical trials in cancer (Calithera/Incyte), while the replenishment of arginine or arginine precursors has been tested in sickle cell disease resulting in a significant reduction in vaso-occlusive complications." (PMID 34341659, 2021). "Increased ARG1 and a decrease level of NO is observed in sickle cell disease (SCD), where during hemolysis, red blood cells (RBCs) release large amounts of ARG1, which contributes to reduction in NO and L-arginine and increased levels of L-ornithine." (PMID 39337272, 2024).
visceral leishmaniasis (6 papers, 2012 to 2025). A severe form of leishmaniasis characterized by irregular bouts of fever, substantial weight loss, swelling of the spleen and liver, and anemia (which may be serious). "A correlation between Arg-1, arginase activity and susceptibility was already shown in patients with visceral leishmaniasis." (PMID 30555475, 2018). "Host arginase 1 (arg1) expression is a significant contributor to the pathogenesis of progressive visceral leishmaniasis (VL), a neglected tropical disease caused by the intracellular protozoan Leishmania donovani." (PMID 24967908, 2014). "We believe that the arginase-1 and cellular exhaustion pathways stimulate each other and constitute interesting targets for immunomodulation in visceral leishmaniasis." (PMID 40621456, 2025). "Similarly, the insulin-like growth factor 1 receptor (IGF1R) has previously been shown to be involved in arginase (Arg1) expression in visceral leishmaniasis and also targeted by rotaviruses, dsRNA viruses, to manipulate the PI3K/Akt pathway and block autophagy." (PMID 35992159, 2022). "In visceral leishmaniasis, the expression of IFN-γ, Arginase-1 and STAT3 impaired macrophage and T lymphocytes responses in vitro." (PMID 40621456, 2025). "On the other hand, monocytes isolated from patients with dermal sequelae of visceral leishmaniasis (post-kala-azar dermal leishmaniasis—PKDL) demonstrated decreased expression of TLR-2/4, simultaneous attenuation of ROS and increased expression of classic M2 markers (CD206, ARG1, and PPARγ)." (PMID 38743668, 2024).